PLK1 (polo like kinase 1)
Diseases named in the same sentence as PLK1 in open-access papers (continued):
Sharing a sentence is not in itself a finding about the gene and the disease.
cancer (continued). "Compared to normal tissues, PLK1 was significantly overexpressed in 18 of 19 analyzed human cancers, with the magnitude of PLK1 overexpression ranging from 2-fold to more than 20-fold." (PMID 37174744, 2023). "A recent study has demonstrated that PLK1 plays a significant role in maintaining cancer stem cell properties." (PMID 38234395, 2023). "As PLK1 inhibitors displayed antitumor efficacy and good tolerability in various human cancer xenograft models as well as in clinical trials, we proposed that PLK1 was an attractive target for the treatment of PH." (PMID 37598171, 2023). "The targeting of PLK1 is regarded as a very promising strategy for cancer treatment, as several inhibitors of this protein have demonstrated promising outcomes in clinical trials." (PMID 37765111, 2023). "Among them, BI2536, a specific PLK1 inhibitor, has been extensively studied as a cytotoxic drug for treating various cancer types." (PMID 37958623, 2023). "In human cancers, PLK1 has been identified to interact with many proteins involved in apoptosis, autophagy, metabolism, inflammation, epithelial-mesenchymal transition, and tumor invasion." (PMID 37174744, 2023). "While significant evidence indicates a connection between PLK1 and human cancer, recent reports have provided conclusive evidence of the in vivo oncogenic effects of PLK1." (PMID 37174744, 2023). "With its essential role in cell proliferation, PLK1 has been determined to be a broad-spectrum anti-cancer target." (PMID 36676076, 2023). "Plk1 plays an important role in the multiple aspects of the cell cycle and is overexpressed in tumors, thereby making the Plk1 an attractive target for cancer therapeutics." (PMID 37154439, 2023). "The inhibition of PLK1 in cancers has been shown to result in the arrest of mitosis, damage to DNA, and static tumors." (PMID 36765811, 2023). "Because it functions as a transcriptional factor, the levels of PLK1 in the nucleus are an important index for the prognosis and diagnosis of cancer." (PMID 36793862, 2023). "Polo-like kinase 1 (PLK1) plays a pivotal role in cell division regulation and emerges as a promising therapeutic target for cancer treatment." (PMID 37958623, 2023). "The results showed that CDKN2A and PLK1 were significantly overexpressed in tumor samples compared to normal samples across the 18 cancer types." (PMID 37000317, 2023). "PLK-1 controls the mitosis stage during cell division, and any dysfunction in PLK-1 regulation leads to cancer cell progression." (PMID 37570823, 2023). "A potential inverse correlation between the expression or activation of pro-proliferative PLK1 and pro-apoptotic p16 has been demonstrated in several cancer studies." (PMID 37958642, 2023). "In previous studies, the activation of the PLK1, MAPK/ERK, JNK/STAT, AKT, and NF-κB pathways was associated with the malignant biology of cancer cells." (PMID 37305386, 2023). "Cell separation can induce upregulation of PLK1 expression, and high levels of PLK1 enhance cancer cell resistance to anoikis through regulation of b-catenin expression." (PMID 37664042, 2023). "To further analyze the relationship between UBE2C and PLK1, we performed a correlation analysis in tumor tissue samples across 33 cancer types, which showed that the correlation coefficient between UBE2C and PLK1 was 0.30–0.93." (PMID 37958642, 2023). "Our findings showed that many important necroptosis molecules in the pan-cancer, including PLK1, MLKL, FASLG, and ZBP1, demonstrated a high level of activation in the apoptosis signaling pathway." (PMID 37000317, 2023). "Will Plk1 inhibitors be a powerful and safe strategy for personalized cancer treatment in the future?" (PMID 36845678, 2023). "Then, we used a series of in vitro experiments to demonstrate that CR can dramatically inhibit the growth of ten cancer cell lines by blocking the PLK1/CDK1/Cyclin B axis." (PMID 37007025, 2023).
cancer (continued). "Together, these results suggested that ST8SIA6-AS1 facilitates KRASG12C-mutant cancer progression, which is primarily dependent on Aurora A/PLK1/c-Myc activation." (PMID 38104151, 2023). "Cancer progression is related to the upregulation of anti-apoptotic proteins such as PLK1 (Polo-like kinase 1), KRAS, and cell growth factor." (PMID 37514088, 2023). "On the other hand, inhibitors of PLK1 showed strong inhibitory effects against different cancer types both in vitro and in vivo, as well as in clinical trials." (PMID 37765111, 2023). "Co-expression network analysis showed that CDCA3, GSG2, KIF2C, NCAPH and PLK1 were positively correlated with ORC1 in cancer, and enrichment analysis showed a correlation with cytosol, ATP binding and cell division." (PMID 37833711, 2023). "PLK1 is a key regulator of the cell cycle and plays an important role in cancer development, progression and drug resistance." (PMID 36855119, 2023). "Polo-like kinase 1 (PLK1), a serine/threonine kinase, acts as an oncogene promoting the malignancy of multiple cancer types." (PMID 37988371, 2023). "As a critical cell cycle regulator, Plk1 is probably the downstream of TGF-β1 which has also been demonstrated in cancer cells." (PMID 37640723, 2023). "Recent studies have suggested that PLK1 is upregulated in various cancers and that PLK1 inhibition has anti-tumor effects." (PMID 37269004, 2023). "The overexpression of PLK1, found in various cancers, promotes cell proliferation, suppresses apoptosis, and is associated with poor prognosis due to its vital role in cell cycle regulation and vast pathway regulation." (PMID 38201556, 2023). "To solve the puzzle, here we set out to make a systematic review and meta-analysis of RCTs to gain insight relative limitation and benefits of Plk1 inhibitors in patients with cancer." (PMID 36845678, 2023). "The PLK1 signaling pathway has been reported to play crucial roles in mitotic catastrophe progression in most cancer cells." (PMID 37305386, 2023). "Preclinical studies have shown promising results for dual BRD4 and PLK1 inhibitors in treating a variety of cancer types." (PMID 37765111, 2023). "PLK1 was extensively studied to examine its function in cell cycle regulation, and it was involved in the development of various cancers." (PMID 36671486, 2023). "Through the inhibition of PLK1, cancer cells are selectively killed, and PD-L1 expression is upregulated in surviving cancer cells, resulting a feedforward targeted delivery of ARAC using PD-L1 antibody-conjugated nanoparticles." (PMID 37008041, 2023). "To validate the effect of UBE2C and PLK1 on the progress of cancer development, we transfected si-PLK into stable knockdown UBE2C cell lines for 72h." (PMID 37958642, 2023). "As cancer cells are often hypersensitive to partial PLK1 inactivation, chemical inhibitors of PLK1 have been developed and tested in clinical trials." (PMID 37639469, 2023). "In NSCLC and multiple other cancers, PLK1 is overexpressed as a key mitotic kinase that stimulates cell proliferation." (PMID 37008041, 2023). "The regulation of these factors by PLK1 and its downstream miRs should be further investigated given the current advancement of PLK1 inhibitors through cancer clinical trials." (PMID 37762595, 2023). "PLK1 is overexpressed in multiple cancers, including NSCLC, and its overexpression is directly associated with poor survival outcomes." (PMID 37174055, 2023). "Co-expression network analysis showed that CDCA3, GSG2, KIF2C, NCAPH and PLK1 were positively correlated with ORC1 in cancer, and the functional enrichment mainly included cytosol, ATP binding and cell division." (PMID 37833711, 2023). "PLK1 expression has been shown to be positively regulated by heterogeneous nuclear ribonucleoprotein K (hnRNPK) in various cancer cell lines." (PMID 36611980, 2023).
cancer (continued). "Multiple studies have elucidated the involvement of PLK1 in governing autophagy and the DNA damage response within cancer cells, rendering it a compelling therapeutic target for diverse malignancies." (PMID 37958642, 2023). "The core effect of CR on ten cancer cell lines is to induce G2/M arrest by inhibiting the PLK1/CDK1/Cyclin B axis." (PMID 37007025, 2023). "CIP2A/p90 can interact with PLK1 and enhance the stability and activity of PLK1, thereby promoting mitosis in human cancer cells." (PMID 36911405, 2023). "Polo-like kinase-1 (PLK1), a serine/threonine protein kinase involved in the initiation, maintenance and termination of mitosis, is highly expressed in a variety of cancers." (PMID 38111074, 2023). "The simultaneous inhibition of BRD4 and PLK1 enzymes by a single small molecule has shown a synergistic effect in the treatment of several types of cancers by increasing apoptosis and decreasing cancer cell proliferation with reduced toxicity." (PMID 37765111, 2023). "Due to its key role in the eukaryotic cell cycles, Plk1 has been one of the most validated drug targets for cancer treatment." (PMID 37640723, 2023). "Our results corroborate those obtained in previous investigations of PLK1 expression in malignant tumors." (PMID 36951624, 2023). "PLK1 inhibition is already considered a potential target for cancer therapy, as it can lead to cancer cell death by interfering with multiple stages of mitosis." (PMID 38201556, 2023). "To date, growing evidence indicates that overexpression of Aurora A/B, cyclin D/E, Cdc20, Skp2, and PLK1 has been frequently detected in all kinds of cancers, and these oncoproteins serve as effective therapeutic targets in the clinic." (PMID 37274251, 2023). "PLK1 is overexpressed in a broad spectrum of human cancers and correlates with unfavorable patients’ outcomes." (PMID 38104151, 2023). "According to our study, although there are certain adverse events in nervous system, digestive system and blood system, Plk1 inhibitors still worked well in safety and prolonged the OS of cancer patients." (PMID 36845678, 2023). "PLK1 is a well-studied serine-threonine kinase known for its function in mitosis and its role in cancer." (PMID 37679323, 2023). "Polo-like kinase 1 (PLK1) has been extensively studied as a target of interest for anti-cancer therapy, considering its role as a master cell cycle regulator." (PMID 37174055, 2023). "PLK1 expression level peaks in G2 and M phases and is highly expressed in cells with active proliferation, like cancer cells." (PMID 37007025, 2023). "On the other hand, stronger PLK1 signaling enhances mitosis to promote the proliferation of cancer cells." (PMID 36993976, 2023). "Each of the seven PLK1 inhibitors have been reported to show cytotoxic activity in a range of cancer cell lines." (PMID 37049713, 2023). "Many studies have shown PLK1 inhibition leading to the death of cancer cells by interfering with multiple stages of mitosis." (PMID 37644431, 2023). "Dysregulation of PLK1 activity can lead to errors in mitosis and contribute to the development of cancer." (PMID 36836481, 2023). "In recent years, PLk1 has emerged as a significant anticancer target, as its inhibition has shown remarkable antitumor effects in various cancer types." (PMID 36805592, 2023). "PLK1, which has been found to be overexpressed in numerous cancers, regulates several important transcription factors and promotes cell proliferation, transformation, and epithelial-to-mesenchymal transition." (PMID 37457582, 2023). "In this review, we not only provide strategies for the selection of Plk1 inhibitors during clinical cancer treatment, but also make reasonable recommendations for the selection of dosages for their pharmacokinetic efficacy." (PMID 36845678, 2023).
cancer (continued). "Our data suggest that combined inhibition of UBE2C and PLK1 can more significantly strongly attenuate the proliferation, migration, colony formation and other malignant phenotypes of pan-cancers while inducing more intense cell cycle arrest and apoptosis." (PMID 37958642, 2023). "In this study, we found that UBE2C and PLK1 were significantly highly expressed in more than 13 cancer tissues." (PMID 37958642, 2023). "Inhibition of PLK1 activity in proliferating cancer cells rapidly induces mitotic arrest and apoptosis." (PMID 36297407, 2022). "Plk1 depletion in cancer cells induces apoptosis, while Plk1 accumulation promotes tumour formation induced by DNA damage." (PMID 36499653, 2022). "Considering its crucial functional node in the oncogenic network, PLK1 has been proposed to serve as a potential target for the treatment of cancer." (PMID 35912180, 2022). "In this review, we will summarize the evidence suggesting the role of PLK1 in response to DNA damage, including DNA repair, cell cycle progression, epithelial to mesenchymal transition, cell death pathways and cancer-related immunity." (PMID 35719948, 2022). "All these biological processes are altered in tumors and, considering that PLK1 is often found overexpressed in several tumor types, its targeting has emerged as a promising anti-cancer therapeutic strategy." (PMID 35719948, 2022). "Then, a prognostic index for all cancer was constructed by the formula MRG = expression level of BIRC5 × (−0.4126) + expression level of PLK1 × 0.39986 + expression level of CDKN3 × 0.2651 + expression level of CYP4B1 × (−0.0955)." (PMID 36293001, 2022). "AKA and Plk1 have a central role in the regulation of cell cycle progression and mitosis, and are frequently overexpressed in human cancers." (PMID 35159005, 2022). "PLK1 knockout suppressed cancer cell survival, induced apoptosis, and increased the sensitivity to chemotherapy drugs." (PMID 35957699, 2022). "First, we analyzed the correlation between PLK1 mRNA levels and prognosis in pan-cancer by GEPIA2 with TCGA database and plotted survival curves for overall survival (OS) and disease-free survival (DFS) respectively." (PMID 36618405, 2022). "PLK1 plays a key role in mitosis, and then affects cell proliferation, which is closely related to the occurrence of a variety of cancers." (PMID 36478716, 2022). "Studies have shown that PLK1 expression is up-regulated in various cancer types, which in turn induces cell proliferation and malignant transformation." (PMID 36311939, 2022). "Firstly, we explored the expressions of PLK1 in various cancers and normal tissues since many previous studies have claimed that abnormal expressions of PLK1 can attract the occurrence of numerous diseases, including cancers." (PMID 36618405, 2022). "First, we evaluated the correlation between ESTIMATE scores (ESTIMATE, immune, and stromal scores) and PLK1 mRNA levels in pan-cancer." (PMID 36618405, 2022). "PLK1, an essential cell cycle regulator and a member of the serine/threonine-protein kinase family, is overexpressed in many human cancers." (PMID 35563183, 2022). "Given that PLK1 expression is elevated in metastases of several cancer types, it is plausible that PLK1 can affect cancer metastasis." (PMID 35379935, 2022). "PLK1 depletion in cancer cells inhibits cell proliferation and induces apoptosis; thus, this is a target for cancer therapy." (PMID 35456196, 2022). "By searching literatures, we found that there was little analysis of the oncogenic roles of PLK1 in pan-cancer." (PMID 36618405, 2022). "Active PLK1 promotes cancer metastasis by upregulating TGF-β signaling and amplifies metastatic properties by forming a positive feedback loop." (PMID 35646063, 2022).
cancer (continued). "PLK1 is pivotal in cell cycle progression and is overexpressed in proliferative tissues, including cancer cells." (PMID 34561554, 2022). "In summary, our results suggested that PLK1 was overexpressed in various cancers and significantly correlated with the poorer prognosis." (PMID 36618405, 2022). "PLK1 is highly overexpressed in various cancer cells, and inhibition of PLK1 leads to mitotic arrest and cell apoptosis." (PMID 35910374, 2022). "Although the results of a series of bioinformatics analyses had confirmed that PLK1 played oncogenic roles in pan-cancer, the experimental verification was more convincing." (PMID 36618405, 2022). "Investigations have also been examined possibility to boosting the response to therapy in different cancers by combining PLK1 inhibitors with chemotherapies." (PMID 35719948, 2022). "Although there has been a mass of researches on the roles of PLK1 in cancer about cell cycle, few analyses of PLK1 about tumor immunity have been conducted." (PMID 36618405, 2022). "The upregulation of PD-L1 suggests that evasion of the immune response is one of the mechanisms exploited by cancer cells that survive PLK1 inhibition." (PMID 35871223, 2022). "Loose of the cell cycle regulation is central to this oncogenic proliferation, and dysregulation in markers (such as E2F1, PLK1, CCNE1, and CCND1) associated with cell cycle mechanism is one of the most prominent molecular aberrations in all cancers." (PMID 35419294, 2022). "The results of pan-cancer analysis implied that PLK1 expression levels were negatively corelated with the multiple TIIs/TILs levels in several cancer types." (PMID 36618405, 2022). "Targeted agent like PLK1 inhibitor has shown to sensitize cancer cells to cisplatin by inducing pyroptosis in oesophageal squamous cell carcinoma." (PMID 36605187, 2022). "Secondly, in order to explore the oncogenic mechanisms of PLK1 in pan-cancer, the top 100 PLK1 positively correlated genes in pan-cancer were obtained to perform enrichment analysis." (PMID 36618405, 2022). "Several specific small molecular PLK1 inhibitors have been developed and entered phase I and II clinical studies for patients with various cancers." (PMID 35844795, 2022). "Several mitotic kinases, namely, PLK1, Aurora kinases, Rho-associated protein kinase 1, and integrin-linked kinase, are considered in this review, as an understanding of the shared machineries between mitosis and metastasis could be helpful for developing new strategies to treat cancer." (PMID 35379935, 2022). "Inhibition of PLK1 selectively kills cancer cells and upregulates PD-L1 expression in surviving cancer cells thereby providing opportunity for ARAC targeted delivery in a feedforward manner." (PMID 35871223, 2022). "A phase III clinical trial for volasertib, an ATP-competitive PLK1 inhibitor, has shown considerable promise for combating cancer cells." (PMID 35517890, 2022). "Aberrant cell division is one of the essential events that contributes to tumorigenesis, in which many cell cycle regulatory proteins, including cyclin D/E, PLK1, Aurora A/B, Skp2, and Cdc20, have been frequently detected in various types of human cancers." (PMID 35912180, 2022). "In this context, targeting PLK1 is an appealing alternative as it is a key regulator of the cell cycle and its activity is often altered in cancer." (PMID 36008466, 2022). "Preliminary and ongoing clinical trials in PLK1 inhibition as an anti-cancer treatment have shown substantial promise." (PMID 34561554, 2022). "First, we confirmed increased expression of PLK1 in the Beta/Duct/Cancer cluster due to increased METTL3 expression." (PMID 35773310, 2022). "We report that PLK1 inhibition upregulates PD-L1 expression in cancer cells, thereby diminishing cytotoxic T cell function." (PMID 35871223, 2022). "PLK1 is overexpressed in many cancers and serves as a well-validated target for new drugs in pre-clinical studies." (PMID 35454120, 2022).